E2F2 (E2F transcription factor 2)
Diseases named in the same sentence as E2F2 in open-access papers (continued):
Sharing a sentence is not in itself a finding about the gene and the disease.
tumor (continued). "For HCC, miR-218 has been validated as a down-regulated genes associated with tumor process through targeting different downstream mRNAs, such as PTEN, E2F2." (PMID 28977866, 2017). "Expression of E2F2 was found to be markedly high in NSCLC samples as compared to normal specimens and was closely associated with clinical stage and tumour size." (PMID 28378523, 2017). "In contrast, loss of E2F2 increased Myc-induced T cell lymphomagenesis in mice, and the reintroduction of E2F2 into E2F2-null tumors resulted in apoptosis of the tumor cells." (PMID 26992224, 2016). "Our results demonstrate that miR-214 has tumor-suppressive activity in HCC through inhibition of E2F2, CDK3 and CDK6." (PMID 26498144, 2016). "Taken together, the in vitro and in vivo results demonstrate that miR-155 functions as a tumor-promoting miRNA by targeting E2F2 in ccRCC." (PMID 26967247, 2016). "The current study has demonstrated that miR-214 is a new tumor-suppressive miRNA in HCC that targets multiple cell-cycle stimulated gene (E2F2, CDK3, and CDK6) promoters." (PMID 26498144, 2016). "A colony formation assay from circulating tumor cells showed a reduction in the amount of colonies formed in the E2F2 null background indicating a block in the early stages of tumor metastasis." (PMID 26682278, 2015). "In that work, a Kaplan-Meier survival plot revealed a significant acceleration in tumor onset when E2F1 was lost and a delay in tumor onset when E2F2 or E2F3 was lost." (PMID 26474282, 2015). "A genetic cross of MMTV-Neu mice into an E2F1 null, E2F2 null, or E2F3 heterozygous background revealed significant changes in tumor progression specifically reductions in tumor latency and metastasis with E2F1 or E2F2 loss." (PMID 26682278, 2015). "In conclusion, the present study provided evidence that miR-218 and miR-520a are downregulated in HCC, and that these miRNAs act as tumor suppressors to inhibit cell proliferation, partly by regulating E2F2 expression." (PMID 25816091, 2015). "This was investigated and validated through traditional genetic studies, and the role of E2F1 and E2F2 was shown in tumor metastasis." (PMID 26682278, 2015). "In a period of 50 days post-cell injection, although transient, the E2F2 knockdown in U87MG cells inhibited tumor development." (PMID 25202354, 2014). "Under standard growth conditions in vitro, the total number of viable tumor cells was significantly lower after 48, 72 and 96 h of E2F2 knockdown compared with that in the NS control group (P=0.0044, P=0.0007 and P=0.0035, respectively)." (PMID 25202354, 2014). "Subcutaneous and orthotopic xenograft models of GBM in nude mice also indicated inhibition of tumor development in vivo, following E2F2 silencing." (PMID 25202354, 2014). "Overall, these concordant findings suggest that E2F2 is an important transcription factor regulating the tumor-initiating capability of human GBM cells." (PMID 25202354, 2014). "Upon E2F2 silencing, in vitro cell proliferation was significantly reduced, as indicated by a time-course analysis of viable tumor cells." (PMID 25202354, 2014). "In GBM, E2F2 was identified as one of the hyper-expressed genes in CD133+ tumor cells, compared with their counterparts, and its expression correlated with malignancy grade." (PMID 25202354, 2014). "The consequence was inhibited tumor cell motility, reduced tumor growth, and inhibited metastasis formation, with an associated down-regulation of miRNA oncogenic target genes, such as C-MYC, E2F2, CDK6, and TGIF2." (PMID 23091478, 2012). "Specifically, E2F2 functions as a tumor suppressor in the skin, since inactivation cooperates with transgenic expression of Myc to enhance tumor development." (PMID 21072181, 2010). "The E2f2−/− mice were prone to early tumor onset with tumors appearing on average 60 days earlier than in their wild-type siblings and there was a significant difference (p<0.0001) between the E2f2+/+ and E2f2−/− tumor curves." (PMID 19749980, 2009).
tumor (continued). "The genes CCNB1IP1, CUL7 and E2F2 are involved in cell cycle control and cell growth and have expression levels in our study that promotes cell growth in the tumours from deceased patients." (PMID 18778486, 2008). "Similarly, the transcription factor E2F2 plays a dual role in GC, contributing to tumor aggressiveness and immune modulation through autophagy suppression." (PMID 40740483, 2025). "E2F2-positive cells were also present near the tumor margins in the CDBA treatment group." (PMID 40316727, 2025). "A wealth of research has substantiated that E2F2 could contribute to the enhancement of tumor cell proliferation, angiogenesis, and invasiveness." (PMID 38807594, 2024). "Besides, IHC staining of Ki‐67 and E2F2 in the xenograft tumours revealed that the reduction in E2F2 level in the exo‐si‐circSTRBP group was accompanied by the lowered level of Ki‐67 staining (p < 0.05)." (PMID 38520208, 2024). "E2F2 acts as an activator is closely related to clinical stage and tumor size." (PMID 38807594, 2024). "Moreover, the dysregulation of cell-cycle-regulated genes (PLK1, CCNB1, CDKN2A, CCNE2, E2F1, and E2F2) by miR-5100 consistently resulted in upregulation in tumor tissues." (PMID 39590378, 2024). "Therefore, this review summarizes the functions and roles of E2F2 in cancer progression, further exploring its contributions to tumor development and identifying potential therapeutic targets." (PMID 38807594, 2024). "Furthermore, clinical research using CDK4/6 inhibitors not only confirmed our original MASH findings but also provided insight into the function and mode of macrophage E2F2 signaling in the context of anti‐tumor immunity." (PMID 39465673, 2024). "Study has demonstrated that E2F2 inactivation could cooperate with transgenic expression of Myc to enhance tumor development in the skin and oral cavity, perhaps by limiting proliferation in response to Myc." (PMID 38807594, 2024). "The expression level of E2F2 was correlated with advanced tumor stage." (PMID 38807594, 2024). "In addition, through TCGA database analysis, we found that NBR1 and E2F2 are highly expressed in tumor tissues, and the expression of E2F2 was inversely proportional to patient prognosis, consistent with our previous results." (PMID 37097629, 2023). "Moreover, the patients with N0 had a significantly lower protein expression level of E2F2 than patients with N3 in tumour samples." (PMID 37047293, 2023). "Moreover, the median protein concentration of E2F2 was higher in HPV-negative patients in the tumour tissues (0.193 vs. 0.056; p-value = 0.03) compared to HPV-positive patients." (PMID 37185737, 2023). "However, unbiased methods are required to furtherly analyze the functions and pathways of E2F2 in tumor immune infiltration in CRC." (PMID 35069909, 2022). "In this study, we first systematically analyzed and identified the critical dysregulated modules and networks as well as the hub genes at the whole genomic level in LUAD, and found that E2F2 is a critical transcription factor that plays a tumor-promoting role in LUAD." (PMID 35844795, 2022). "Moreover, GSE9348 data set was also downloaded to be analyzed and the results found that E2F2 was significantly decreased in tumor tissues of patients with early stage CRC compared with nomal tissues (p < 0.01)." (PMID 35069909, 2022). "E2F2 has also been suggested as a specific tumor suppressor in Myc-induced T cell lymphomagenesis." (PMID 35069909, 2022). "Finally, since tumor microenvironment is an important participant of tumor initiation and progression, the relevance between E2F2 expression and immune cell infiltration of CRC was also discussed." (PMID 35069909, 2022). "E2F2 can function as either a tumor promoter or suppressor depending on the environment." (PMID 35069909, 2022). "In addition, another study about 119 LC biopsies has reported that E2F2 is preferentially expressed in adenocarcinomas subtypes vs other tumor types (squamous and others)." (PMID 36245705, 2022).
tumor (continued). "There is a correlation between the expression of E2F2 and the immune infiltrating cells in GC, which suggests that E2F2 may play a potential role in tumor cellular immunity." (PMID 34091441, 2021). "WB test showed that E2F2 protein in nude mice tumor tissues decreased evidently." (PMID 34433131, 2021). "It was found that knocking down circ_RPPH1 could hinder the growth of tumor volume and mass in nude mice, which was achieved by miR-146b-3p/E2F2 axis." (PMID 34433131, 2021). "Whether E2F2 is a key factor in the mediation of immunotherapy and how E2F2 mediates autophagy to regulate tumor immune cells requires further research." (PMID 34091441, 2021). "We first detected the expression of E2F2 in various tumor types." (PMID 34091441, 2021). "E2F2 also had potential modulatory effects on tumor immunity." (PMID 34091441, 2021). "Hence, an overexpression of Let-7a, which, by negatively targeting E2F2 is responsible for inhibiting cell proliferation, can function as a tumor suppressor." (PMID 33503899, 2021). "In addition to their well-characterized roles in cell cycle control, E2F2 play key roles in mediating tumor development and metastasis." (PMID 35003347, 2021). "After analyzing over a dozen cancers, we found that E2F2 is highly expressed in many tumor types." (PMID 34091441, 2021). "Furthermore, the ACP samples were subjected to immunohistochemistry analysis, which demonstrated strong staining of KLF5 and E2F2 in the whole tumor tissues, especially in the cystic wall." (PMID 35155179, 2021). "Loss of E2F2 and E2F3 is related to a significant delay in tumor onset." (PMID 32806777, 2020). "E2F2 plays dual roles in the occurrence and development of tumor." (PMID 32117628, 2020). "The expression levels of E2F2/4/5/7/8 were correlated with advanced tumor stage." (PMID 29754146, 2018). "E2F2 is a tumor activator in NSCLC and an independent indicator of OS in patients with NSCLC." (PMID 29754146, 2018). "In such tumours, miR-99a expression inversely correlated with E2F2 expression." (PMID 29072692, 2017). "The results obtained indicated that miR-155 acts as an oncogene in ccRCC progression and that E2F2 may serve as a tumor suppressor." (PMID 26967247, 2016). "Moreover, transfection with E2F2 siRNA also significantly increased tumor cell apoptosis, accompanied by a cell-cycle arrest at the G1 phase." (PMID 27174918, 2016). "We also discover, for the first time, that E2F2 acts as a tumor suppressor in ccRCC." (PMID 26967247, 2016). "In addition, we found that knockdown of E2F2 reduced tumor cell migration and invasion capacity in these twoSGC-7901 and MGC-803 cell lines." (PMID 27174918, 2016). "Other published work noted that E2F2 loss in Wap-Myc mice decreased time to tumor onset and did not describe a metastatic phenotype." (PMID 26474282, 2015). "There was a significant delay in tumor latency associate with E2F1, E2F2 and E2F3 loss." (PMID 26682278, 2015). "Interestingly, the genetic crosses to delete E2F2 in Myc induced tumors have provided different results for tumor latency." (PMID 26474282, 2015). "Similar results were observed by the MTT assay, based on the activity of mitochondrial succinate dehydrogenase, which indicated significantly lower numbers of viable tumor cells after 72 h and 96 h of E2F2 knockdown, compared with the controls (P<0.0001 for the two time points)." (PMID 25202354, 2014). "The function of E2F2 is less characterized relative to other members of the E2F family, and its involvement in tumorigenesis remains a matter of debate, since evidence of both tumor suppression and pro-oncogenic activities have been reported." (PMID 25202354, 2014). "Moreover, the pleiotropic miR-24, in addition to its regulation of ARF, has been shown to repress expression of MYC and E2F2, which are important in driving proliferation and imperative to tumor growth." (PMID 22336108, 2012).
tumor (continued). "Notably, the E2f2+/− mice exhibited a median tumor-free span of 92 days and a significantly accelerated course of disease compared to wild-type siblings (p<0.0001)." (PMID 19749980, 2009). "An alteration in the apoptotic potential of Myc could account for the differences in Myc-initiated tumor onset among wild type, E2f2-null and E2f4-null animals." (PMID 19749980, 2009). "Distinct tumor types emerged with their relative proportions influenced by E2F2 and E2F4 status." (PMID 19749980, 2009). "Besides the limited evidence demonstrating that E2F2 could suppress tumor progression, an increasing number of experiments indicated that E2F2 was closely related to the occurrence of multiple cancer types." (PMID 38807594, 2024). "E2F2 could potentially promote tumour progression and metastasis." (PMID 37185737, 2023). "However, E2F2 can also serve as a tumor suppressor in many malignancies." (PMID 35069909, 2022). "Therefore, we postulated that ZNF750 may be a crucial mediator on Ezh2, leading to reduced tumor growth, metastasis, and the E2F2 was involved in its regulation." (PMID 35003347, 2021). "However, the expression of E2F2 in patients with PAAD is related to the stage of the tumor." (PMID 33604289, 2020). "Moreover, sequencing identified that loss of miR-4319 in TNBC and presence of miR-4319 was shown to reduce malignant potential of TNBC cells as it suppresses the self-renewal and formation of tumor spheres in TNBC through E2F2 as well as inhibits tumor initiation and metastasis." (PMID 30871273, 2019). "In addition, miR-155 functions as a tumor-promoting microRNA by targeting E2F2 in ccRCC." (PMID 28740578, 2017). "Notably, tumor suppressive activities of E2F2 have been reported in MYC triggered tumorigenesis." (PMID 27081696, 2016). "Interestingly, none of these growth inhibitory targets of E2F were upregulated after IFI6 knockdown, which may in part explain why IFI6-mediated upregulation of E2F2 results in dysregulated DNA replication and tumor growth inhibition." (PMID 27608486, 2016). "However, one might predict that there are specific downstream targets of E2F1 or E2F2 that mediate discreet steps in the development of tumor metastasis." (PMID 26682278, 2015). "Reported biomarkers exhibiting comparable dysregulation in both tumor and peritumor tissues include MDM2, E2F2, CDKN2A/p16, ETS-1, MGMT, and multiple microRNAs (e.g., miR-21, miR-96-5p, miR-145-5p)." (PMID 41683639, 2026). "Consistent with tumor suppression, effectors of tumorigenesis (Myc, Myb, NKX2-3, and TRIM24), metastasis (NFE2L2), oncogenic transformation (FOXM1), and cell cycle (E2F2 and E2F3) were also inhibited in the presence of PRKN." (PMID 39213189, 2024). "This in turn, leads to increased production of important cancer-inducing genes such as RAS and MYC, as well as cell-cycle regulators like E2F2, CDK6, and CCND2, all of which have significant effects on tumor growth and metastasis." (PMID 39641053, 2024). "Nuclear receptors RORa, NR2F6 and HNF4G are uncovered as candidate transcriptional drivers of these cells whilst closure of binding sites for E2F2 and E2F4 indicate post-treated tumour having low proliferative capacity." (PMID 39341888, 2024). "PRR34-AS1 lncRNA increased E2F2 and SOX12 expression by sponging miR-296–5p in HCC cells, thus stimulating the Wnt/β-catenin pathway and promoting cell proliferation and tumor progression." (PMID 39641053, 2024). "Based on the key role of E2F2 in the occurrence of cancer through the regulation of cell cycle process, further research on the regulatory mechanism of E2F2 in the process of tumor formation may provide new research ideas in the control of tumor growth and the development of novel anti-tumor drugs." (PMID 38807594, 2024). "The median protein concentrations of E2F2, MDM2 and p16 were higher in the tumour tissue than in the margin samples." (PMID 37185737, 2023).
tumor (continued). "Disruption of E2F2/NBR1/MHC‐I signaling by shRNA or blockade of the corresponding antibodies largely abolished the tumor‐supportive effects of LINC01232 and inhibited tumor growth driven by M2‐type macrophages." (PMID 37097629, 2023). "Disruption of LINC01232/E2F2/NBR1/MHC‐I by shRNA or blocking the corresponding antibodies largely diminished the tumor‐supportive effects of LINC01232 and suppressed tumor growth driven by M2‐type macrophages." (PMID 37097629, 2023). "In this study, we found that TAMs secrete exosomes rich in LINC01232 into tumor cells and that LINC01232 directly binds E2F2 and promotes E2F2 entry into the nucleus; the two synergistically promote the transcription of NBR1." (PMID 37097629, 2023). "Exo carrying miR-631 mimic declined E2F2 and phosphorylation of PI3K/Akt in tumor tissues, while Exo carrying miR-631 inhibitor was in the opposite." (PMID 35353027, 2022). "Gene group 2 displayed a significant upregulation of E2F transcription activators (E2F1, E2F2, E2F3, and E2F6) and tumor-specific transcription factors (MYCN, RUNX1, and GABPB1) in advanced Rb." (PMID 35626705, 2022). "In an additional set of Rb tumor samples and pediatric healthy controls, we further validated differences in the expression of HK1 and E2F2." (PMID 35626705, 2022). "The tumor suppressive genes of the NRGPI (suppressed in NRGPI-High subgroup), the E2F2 and EFNA3, were regulated by a group of 4 microRNAs (E2F2: hsa-miR-490-3p and hsa-miR-145-5p; EFNA3: hsa-let-7c-5p and hsa-miR-133a-3p)." (PMID 36389725, 2022). "Therefore, we hypothesized that E2F2 may be a control tower regulating tumor aggressiveness in GBM." (PMID 36033456, 2022). "In summary, we have not demonstrated that a change in expression profiles of CDKN2A, MDM2, E2F2 and LTF genes in tumour and margin tissues has a significant impact on the pathogenesis of OSCC." (PMID 36551770, 2022). "Unexpectedly, the correlation analysis between the upstream regulator's analysis identified MYBL2, E2F2, CBX3, FOXM1, and E2F1, which were significantly elevated in the LUAD or LIHC tumor groups, with a strongly correlated value with utility as biomarkers." (PMID 35404841, 2022). "For the “Pathway in cancer” pathway, a total of 18 risk lncRNAs synergistically regulated ER (ESR1), E2F (E2F1 and E2F2), CyclinA1 (CCND1), and Survivin (BIRC5), which indirectly leads to tumor cell proliferation." (PMID 34149805, 2021). "Upregulated genes included several genes involved in the control of the cell cycle like E2F2, cyclin-dependent kinase 1 (CDK1) and MCM2 but also cytokine gene network with crucial effects on inflammation and tumor immunology as well." (PMID 33499054, 2021). "In terms of DFS, patients with increased E2F1 (p < 0.001), E2F2 (p < 0.001), E2F7 (p < 0.001), and E2F8 (p = 0.001) tumor expression have a poorer prognosis." (PMID 33061852, 2020). "Inactivation of RB1 expression in tumor cells leads to the deregulation of activity of transcription factors E2F1, E2F2, and E2F3, which control the expression of genes involved in differentiation, development, proliferation, and apoptosis." (PMID 32429447, 2020). "The results showed that the expression levels of E2F2, E2F3, E2F6, and E2F8 are significantly correlated with the tumor stage of PAAD patients, while the expression levels of E2F1, E2F4, E2F5 and E2F7 are not correlated with the tumor stage of PAAD patients." (PMID 33604289, 2020). "E2F2 and EMR2 are preferentially expressed in adenocarcinomas subtypes versus other tumour types (squamous and others)." (PMID 29072692, 2017). "Therefore, E2F2 may act as either a tumor suppressor or an activator in different cancer type." (PMID 28740578, 2017). "Immunohistochemistry and Western blot also consistently showed that the expression of E2F2, CDK3, and CDK6 in miR-214-overexpressing cell-line tumor models were lower than those in the vector-control tumors." (PMID 26498144, 2016).